SDHAF3 (succinate dehydrogenase complex assembly factor 3)
Description:
Plays an essential role in the assembly of succinate dehydrogenase (SDH), an enzyme complex (also referred to as respiratory complex II) that is a component of both the tricarboxylic acid (TCA) cycle and the mitochondrial electron transport chain, and which couples the oxidation of succinate to fumarate with the reduction of ubiquinone (coenzyme Q) to ubiquinol. Promotes maturation of the iron-sulfur protein subunit SDHB of the SDH catalytic dimer, protecting it from the deleterious effects of oxidants. May act together with SDHAF1.
Synonyms: ACN9; DC11; Sdh7; LYRM10
Tractability: No criterion of Open Targets' tractability assessment is met for any kind of drug.
Gene: Protein-coding gene on chromosome 7 (97,117,698 to 97,181,763, forward strand). Ensembl gene ENSG00000196636.
Subcellular location: Mitochondrion matrix
Subcellular location (Human Protein Atlas): Mitochondria
Pathways (Reactome):
Metabolism: Maturation of TCA enzymes and regulation of TCA cycle
Gene Ontology:
Biological process: mitochondrial respiratory chain complex II assembly; regulation of gluconeogenesis
Cellular component: mitochondrion; mitochondrial matrix
Genetic constraint (gnomAD): Loss-of-function variants: 19 observed, 14.1 expected, observed/expected ratio (o/e) 1.35, 90% interval 0.93 to 1.85. The upper end of that interval is the gene's LOEUF score, 1.85, which puts it in group 6 of 6, group 1 being the genes least tolerant of losing a copy. Missense variants: 200 observed, 164.94 expected, observed/expected ratio (o/e) 1.21, 90% interval 1.08 to 1.36. Synonymous variants: 72 observed, 63.75 expected, observed/expected ratio (o/e) 1.13, 90% interval 0.93 to 1.37.
Homologues: Orthologues: chimpanzee SDHAF3 (98% identical), macaque SDHAF3 (94% identical), guinea pig SDHAF3 (84% identical), mouse Sdhaf3 (82% identical), rat Sdhaf3 (82% identical), tropical clawed frog sdhaf3 (58% identical), zebrafish sdhaf3 (56% identical), Drosophila melanogaster Sdhaf3 (37% identical), Caenorhabditis elegans F25H9.7 (34% identical).
Diseases named in the same sentence as SDHAF3 in open-access papers:
SDHAF3 is named in the same sentence as 10 diseases in open-access papers, as found by Europe PMC text mining. Sharing a sentence is not in itself a finding about the gene and the disease. The quoted sentences say what the papers report.
pheochromocytoma (3 papers, 2017 to 2022). "Taken together, we hypothesized that mutations within the newly identified SDH assembly factor, SDHAF3, may be associated with the pathogenesis of pheochromocytoma and/or paraganglioma syndromes." (PMID 28738844, 2017). "We therefore hypothesized that mutations within the newly identified SDH assembly factor, SDHAF3, may be associated with the pathogenesis of pheochromocytoma and/or paraganglioma syndromes." (PMID 28738844, 2017). "In 6 of them, we revealed the existence of pathogenic/likely pathogenic variants of genes encoding for components of the SDH complex (SDHB, SDHD, SDHAF3, and SDHAF4), confirming their high mutation frequency not only in paragangliomas and pheochromocytomas but also in VPGLs as distinct tumor types." (PMID 32948195, 2020).
bipolar disorder (1 paper, 2024). A disorder of the brain that causes unusual shifts in mood, energy, activity levels and the ability to carry out day-to-day tasks. "NDUFV2 was upregulated in bipolar disorder but downregulated in ketosis, whereas CYCS and SDHAF3 were downregulated in bipolar disorder but upregulated in ketosis." (PMID 39125835, 2024).
schizophrenia (1 paper, 2024). A major psychotic disorder characterized by abnormalities in the perception or expression of reality. "The gene SDHAF3 also showed a discordant pattern, as it was downregulated in schizophrenia and upregulated in ketosis." (PMID 39125835, 2024).
tumor (3 papers, 2017 to 2022). "The protective gene SDHAF3 has been found to be involved in the maturation of succinate dehydrogenase (SDH) genes, which are known as classical tumor suppressors." (PMID 37066112, 2022).
infection (1 paper, 2022). The state of being infected such as from the introduction of a foreign agent such as serum, vaccine, antigenic substance or organism. "It is most likely that the infection hampered the tricarboxylic acid (TCA) cycle, because several genes (such as Sdhaf3, Sucla2, Idh3a and Mdh2) encoded the key enzymes in TCA cycle were significantly downregulated." (PMID 36618398, 2022).
SDHAF3 also shares sentences with these, for which no sentence is quoted: malaria (3 papers); paraganglioma (2); Alzheimer disease (1); anemia (1); major depressive disorder (1).